ITIH6 (inter-alpha-trypsin inhibitor heavy chain family member 6)
Synonyms: ITIH5L; UNQ6369; dJ14O9.1
Tractability: Antibody: UniProt places it where antibodies can reach, with medium confidence; UniProt predicts a signal peptide or a membrane-spanning region; its Gene Ontology location is reachable by antibodies, with medium confidence.
Gene: Protein-coding gene on chromosome X (54,748,918 to 54,798,255, reverse strand). Ensembl gene ENSG00000102313.
Subcellular location: Secreted
Gene Ontology:
Molecular function: protein binding; serine-type endopeptidase inhibitor activity
Biological process: hyaluronan metabolic process
Cellular component: extracellular region
Homologues: Orthologues: chimpanzee ITIH6 (99% identical), macaque ITIH6 (95% identical), rabbit ITIH6 (80% identical), rat Itih6 (70% identical), mouse Itih6 (69% identical), tropical clawed frog itih6 (39% identical), zebrafish itih6 (26% identical). Paralogues in human: ITIH5 (25% identical), ITIH3 (22% identical), ITIH2 (21% identical), ITIH4 (21% identical), ITIH1 (21% identical), PARP4 (12% identical), VWA3B (10% identical), VWA5B1 (10% identical), VWA5A (10% identical), VWA5B2 (10% identical), VWA3A (9% identical).
Diseases named in the same sentence as ITIH6 in open-access papers:
ITIH6 is named in the same sentence as 4 diseases in open-access papers, as found by Europe PMC text mining. Sharing a sentence is not in itself a finding about the gene and the disease. The quoted sentences say what the papers report.
autism (1 paper, 2017). Persistent deficits in social interaction and communication and interaction as well as a markedly restricted repertoire of activity and interest as well as repetitive patterns of behavior. "Of these variants, 4 were found in genes not previously implicated in ASD nor listed in Autism databases (DDX26B, HTATSF1, ITIH6 and PLP1)." (PMID 28720891, 2017).
cancer (1 paper, 2017). A tumor composed of atypical neoplastic, often pleomorphic cells that invade other tissues. "The remaining variants were located in genes of largely unknown function such as (CFAP47, ITIH6 and ZNF630) or in cancer-associated genes namely; INTS6L90, 91 and SSX392." (PMID 28720891, 2017).
ITIH6 also shares sentences with these, for which no sentence is quoted: autism spectrum disorder (1 paper); melanoma (1).